MCM9 (minichromosome maintenance 9 homologous recombination repair factor)
Diseases named in the same sentence as MCM9 in open-access papers (continued):
Sharing a sentence is not in itself a finding about the gene and the disease.
glioma (1 paper, 2022). A benign or malignant brain and spinal cord tumor that arises from glial cells (astrocytes, oligodendrocytes, ependymal cells). "We utilized the cox proportional hazard model and found that macrophages, neutrophils, MCM8, and MCM9 expression were associated with a poor prognosis of glioma." (PMID 36465369, 2022). "We utilized the cox proportional hazard model and found that macrophages, neutrophils, MCM8, and MCM9 expression were related to the poor prognosis of glioma patients." (PMID 36465369, 2022). "CNV analysis results confirmed that copy number variations of MCM7, MCM9, and MCM3 were significantly positively correlated with its expression in glioma." (PMID 36465369, 2022). "In this research, we uncovered that copy number variations of MCM7, MCM9 and MCM3 were significantly positively correlated with its expression in glioma." (PMID 36465369, 2022). "Receiver operator characteristic (ROC) curve analysis results confirmed that MCM2-MCM7, MCM9, and MCM10 had high accuracy (AUC > 0.80) in predicting glioma." (PMID 36465369, 2022).
lung carcinoma (1 paper, 2021). "In terms of survival rate, MCM1 was found to negatively associate with OS, while the high level of MCM9 was related to better OS, which was not consistent the role of other MCMs on the prognosis of lung cancer." (PMID 33936158, 2021).
lymph node metastasis (1 paper, 2016). "However, we just found that MCM9 over-expression was markedly associated lymph node metastasis of PC." (PMID 27695057, 2016). "Analytic results suggested that MCM4 over-expression was detected in patients with aggressive T stage, and MCM9 was over-expressed in patients with lymph node metastasis." (PMID 27695057, 2016).
myelodysplastic syndrome (1 paper, 2023). A clonal hematopoietic disorder characterized by dysplasia and ineffective hematopoiesis in one or more of the hematopoietic cell lines. "Moreover, MCM8 and MCM9 KO mice are predisposed to hematopoietic proliferation anomalies with the development with the age of myeloid tumors that are similar to myelodysplastic syndromes in humans." (PMID 36769638, 2023).
neuroblastoma (1 paper, 2021). Neuroblastoma (NB) is the most common solid, extracranial childhood tumor. "Kaplan–Meier curve analysis also showed that high expression of MCM genes, except for MCM9, were associated with poor survival in neuroblastoma, even in patients with MYCN-non-amplified tumor." (PMID 35056094, 2021). "We found that expression of several MCM genes, except for MCM9, positively correlated with advanced disease stage and was relatively lower in stage 4S neuroblastoma, which usually exhibits better prognosis compared with other stages." (PMID 35056094, 2021).
non-small cell lung carcinoma (1 paper, 2015). A group of at least three distinct histological types of lung cancer, including non-small cell squamous cell carcinoma, adenocarcinoma, and large cell carcinoma. "To test whether the cancer-specific loss of MCM9 affected HR repair, we compared the ability of NCI-H2291 and NCI-H1299, a control non-small cell lung cancer cell line, to cope with cisplatin-induced DNA damage." (PMID 26215093, 2015). "Several cancer cell lines, including a non-small cell lung cancer cell line, NCI-H2291, also have a homozygous deletion of the MCM9 locus." (PMID 26215093, 2015).
prostate carcinoma (1 paper, 2015). A carcinoma that arises from epithelial cells of the prostate gland. "The expression level of the MCM9 protein is correlated to the cisplatin resistance of some prostate cancer cell lines and a cancer-derived mutation of MCM8 inactivated MCM8." (PMID 26215093, 2015). "The cisplatin resistance of these prostate cancer cell lines was remarkably correlated to the amount of MCM9 protein expressed." (PMID 26215093, 2015). "In addition, we found that several prostate cancer cell lines do not have deletions in MCM9, but express lower levels of the MCM9 protein compared with HEK293T cells." (PMID 26215093, 2015).
rectal adenocarcinoma (1 paper, 2020). "MCM9 was 1.926-fold in colon and 1.999-fold in rectal adenocarcinoma samples lower than relevant normal tissues." (PMID 32597491, 2020).
sarcoma (1 paper, 2021). A usually aggressive malignant neoplasm of the soft tissue or bone. "Using CCLE datasets, we found that MCM8 and MCM9 were both overexpressed in che cell line of sarcoma." (PMID 34239894, 2021). "In sarcoma, most of MCM members were highly expressed in cancer tissues, except for MCM8 and MCM9." (PMID 34239894, 2021).
triple-negative breast carcinoma (1 paper, 2025). An invasive breast carcinoma which is negative for expression of estrogen receptor (ER), progesterone receptor (PR), and human epidermal growth factor receptor 2 (HER2). "The intersection of these methods aids the confident identification of the core set of essential genes, such as MCM9, as potential gene targets to overcome triple-negative breast cancer." (PMID 41375077, 2025).
trisomy 21 (1 paper, 2021). A chromosomal disorder consisting of the presence of an extra chromosome 21. "Third, we could not explore the effect of the MCM9 risk variants on the recombination profile of Ch21 from siblings of the trisomy 21 proband." (PMID 33750944, 2021).
Turner syndrome (1 paper, 2017). Turner syndrome is a chromosomal disorder associated with the complete or partial absence of an X chromosome. "When this is the case, the underlying pathogenetic mechanism of follicle depletion are heterogeneous ranging from genetic (Turner’s syndrome, mutations in the genes FMR-1, BMP-15, Foxl2, and recently identified MCM9, SYCE1, STAG3) to auto-immune and iatrogenic causes." (PMID 29176793, 2017).
cancer (18 papers, 2015 to 2025). A tumor composed of atypical neoplastic, often pleomorphic cells that invade other tissues. "Due to the limited number of families with biallelic germline MCM8/MCM9 variants described so far, the complete spectrum of phenotypic manifestations and accurate cancer risk estimates remains uncertain." (PMID 40684266, 2025). "None of the family members with homozygous mutations in MCM8 or MCM9 genes had cancer at the time of investigation, but all of them were premenopausal." (PMID 26119146, 2015). "As the homozygotic MCM9 variant subjects are all <30 years of age, they may have been too young to have developed cancers at the time of the study." (PMID 36769638, 2023). "MCM8 and MCM9 play important roles in DNA double-strand repair mechanisms and disordered function of these proteins has been associated with primary gonadal failure and a potentially increased cancer risk." (PMID 36769638, 2023). "Epigenetic suppression of MCM9 predisposes cancer cells to cisplatin sensitivity." (PMID 31581661, 2019). "In addition, SBS1 and SBS5—alongside SBS93 and SBS40, both of unknown origin—were the most prominent signatures in metastasized CRCs from seven individuals with monoallelic MCM8 or MCM9 variants in the HMF cancer-specific cohort." (PMID 40684266, 2025). "Therefore, epigenetic suppression of MCM9 could also predispose cancer cells to cisplatin sensitivity." (PMID 26215093, 2015). "Given the uncertain range of phenotypic manifestations and unclear cancer risk estimates, this study aimed to delineate the molecular and clinical characteristics of biallelic germline MCM8/MCM9 variant carriers." (PMID 40684266, 2025). "In TCGA Pan-Cancer Atlas dataset, insights into the somatic mutational behavior of MCM8 and MCM9 were gained through the observation of copy-number alterations in both genes." (PMID 40684266, 2025). "In the HMF cancer-specific cohort, four monoallelic MCM8 and three monoallelic MCM9 variant carriers meeting the pathogenicity-based filtering criteria were identified with CRC." (PMID 40684266, 2025). "Further studies are essential to accurately assess cancer risk and determine the causative role of MCM8/MCM9 deficiency in cancer predisposition." (PMID 40684266, 2025). "Knockout of MCM8 or MCM9 selectively increases cisplatin sensitivity in specific cancer cells such as HCT116 and HeLa cells." (PMID 36776764, 2023). "Prompted by these findings, we re-evaluated a family with an MCM9 pathogenic variant, previously evaluated at our medical center for POI, and revealed that three siblings had early-onset cancer." (PMID 34556653, 2021). "Mutations in MCM8 and MCM9 in humans are linked to premature ovarian failure (POF), amenorrhea, sterility, and cancer." (PMID 33539926, 2021). "An earlier study has shown that the deletion of MCM9 produced a functional defect of HR repair in cancer." (PMID 31581661, 2019). "Homozygous deletion of the MCM9 found in various cancers sensitizes a cancer cell line to interstrand-crosslinking (ICL) agents." (PMID 26215093, 2015). "We show that a naturally occurring homozygous deletion of the MCM9 sensitizes a cancer cell line to ICL reagents and leads to the HR defect." (PMID 26215093, 2015). "Nevertheless, MCM9 has not been defined as a cancer predisposition gene and is not tested in targeted panels." (PMID 34556653, 2021). "Moreover, a review of the literature on MCM9 carriers revealed that of nine bi-allelic carriers reported, eight had early-onset cancer." (PMID 34556653, 2021). "Instead, several human cancer genomes show homo and heterozygous deletions in MCM9 coding regions, many missense mutations in MCM8 and MCM9, and altered expression levels that correlate with aggressive clinical features and poorer long-term survival in several human cancers." (PMID 33539926, 2021). "In addition, a cancer cell line having homozygous deletion of the MCM9 locus exhibits inefficient HR and high sensitivity to ICL reagents." (PMID 26215093, 2015).
cancer (continued). "This rarity may have contributed to the absence of biallelic MCM8/MCM9 variants in the cancer-specific cohorts and could have influenced the enrichment analysis of these variants in the 100000 Genomes Project and 200000 UK Biobank." (PMID 40684266, 2025). "Therefore, the MCM8-9 complex facilitates DNA resection by the MRN complex during HR repair, genetic or epigenetic inactivation of MCM8 or MCM9 are seen in human cancers, and genetic inactivation of MCM8 may be the basis of a POF syndrome." (PMID 26215093, 2015). "Thus, deletion of MCM9 produces a functional defect of HR repair in this cancer cell line." (PMID 26215093, 2015). "MtrBTN2 cancer was found to express at higher levels a significant panel of transcripts of genes involved in the DNA homologous recombination (HR) (42.Double-strand break repair), such as BABAM1, ZSWIM7, RAD51L, RAD54L, MRE11, MCM9 and TONSL." (PMID 37816387, 2023). "No other types of cancer were reported in the monoallelic MCM9 group." (PMID 40684266, 2025). "However, these clock-like mutational processes, commonly found in most CRCs without specific DNA repair defects and in many other cancer types, were not more prevalent in tumors from MCM8/MCM9 variant carriers than in those from our wild-type control." (PMID 40684266, 2025). "MCM8 and MCM9, which form a stable complex, were among the most abundant proteins identified, suggesting that HORMAD1 might have a functional link with MCM8–MCM9 complex in cancer cells." (PMID 32647118, 2020).
tumor (9 papers, 2015 to 2025). "The expression of eight MCM genes (excluding MCM1 and MCM9) was significantly higher in the tumor stage 1–4 subgroups than that in normal lung tissues." (PMID 36445337, 2022). "MCM2, MCM3, MCM6, MCM8, MCM9, and MCM10 groups significantly varied and associated with the tumor stages." (PMID 34490114, 2021). "In addition, variants in MMR pathway genes, MSH3, MSH6, LIG1, MCM9, and POLD3, were associated with relatively high MSI score and/or high mutational burden in 6 tumor samples." (PMID 41353477, 2025). "The co-expression relationship of MCM1-10 has also been verified in the LUAD tumor tissues, we observed that these MCM genes also significantly positive co-expressed with each other except MCM9." (PMID 31323040, 2019). "A comparison of the distribution of MCM genes between tumor and adjacent normal lung tissues showed MCM2-8 and MCM10 to be significantly up-regulated in LUAD tumor tissues in TCGA cohorts, whereas the SRF and MCM9 were significantly down-regulated in the same." (PMID 31323040, 2019). "MCM5 (40%), MCM6 (45.5%) and MCM9 (25%) were moderately higher in tumor tissues than in normal tissues, and MCM10 was negative in most (91.7%) tumor tissues." (PMID 34859821, 2021). "As expected, in our report, the expression of MCM8 and MCM9 was not significantly higher in EC and was even lower in the tumor tissue, but MCM10 was highly expressed in tumors." (PMID 34859821, 2021). "However, MCM8 or MCM9 defects may not always be linked with a MMR-deficient or MSI-positive tumor." (PMID 32841224, 2020). "However, the expression of MCM9 in tumor tissues was not significant." (PMID 34404366, 2021).
MCM9 also shares sentences with these, for which no sentence is quoted: Lynch-like syndrome (2 papers); adenoma (1); clear cell carcinoma of the cervix (1); colonic adenomas (1); colonic polyps (1); colorectal polyp (1); endometrial endometrioid adenocarcinoma (1); endometrial mixed adenocarcinoma (1); endometrial serous adenocarcinoma (1); epilepsy (1); gastric cancer (1); hepatocellular carcinoma (1); hypothyroidism (1); myeloid tumors (1); oligospermia (1); Onset (1); ovarian dysgenesis (1); rectal polyps (1).